PAK1 (p21 (RAC1) activated kinase 1)
Description:
Protein kinase involved in intracellular signaling pathways downstream of integrins and receptor-type kinases that plays an important role in cytoskeleton dynamics, in cell adhesion, migration, proliferation, apoptosis, mitosis, and in vesicle-mediated transport processes. Can directly phosphorylate BAD and protects cells against apoptosis (By similarity). Activated by interaction with CDC42 and RAC1. Functions as a GTPase effector that links the Rho-related GTPases CDC42 and RAC1 to the JNK MAP kinase pathway. Phosphorylates and activates MAP2K1, and thereby mediates activation of downstream MAP kinases (By similarity). Involved in the reorganization of the actin cytoskeleton, actin stress fibers and of focal adhesion complexes. Phosphorylates the tubulin chaperone TBCB and thereby plays a role in the regulation of microtubule biogenesis and organization of the tubulin cytoskeleton. Plays a role in the regulation of insulin secretion in response to elevated glucose levels. Part of a ternary complex that contains PAK1, DVL1 and MUSK that is important for MUSK-dependent regulation of AChR clustering during the formation of the neuromuscular junction (NMJ) (By similarity). Activity is inhibited in cells undergoing apoptosis, potentially due to binding of CDC2L1 and CDC2L2. Phosphorylates MYL9/MLC2 (By similarity). Phosphorylates RAF1 at 'Ser-338' and 'Ser-339' resulting in: activation of RAF1, stimulation of RAF1 translocation to mitochondria, phosphorylation of BAD by RAF1, and RAF1 binding to BCL2. Phosphorylates SNAI1 at 'Ser-246' promoting its transcriptional repressor activity by increasing its accumulation in the nucleus. In podocytes, promotes NR3C2 nuclear localization (By similarity). Required for atypical chemokine receptor ACKR2-induced phosphorylation of LIMK1 and cofilin (CFL1) and for the up-regulation of ACKR2 from endosomal compartment to cell membrane, increasing its efficiency in chemokine uptake and degradation. In synapses, seems to mediate the regulation of F-actin cluster formation performed by SHANK3, maybe through CFL1 phosphorylation and inactivation (By similarity). Plays a role in RUFY3-mediated facilitating gastric cancer cells migration and invasion. In response to DNA damage, phosphorylates MORC2 which activates its ATPase activity and facilitates chromatin remodeling. In neurons, plays a crucial role in regulating GABA(A) receptor synaptic stability and hence GABAergic inhibitory synaptic transmission through its role in F-actin stabilization (By similarity). In hippocampal neurons, necessary for the formation of dendritic spines and excitatory synapses; this function is dependent on kinase activity and may be exerted by the regulation of actomyosin contractility through the phosphorylation of myosin II regulatory light chain (MLC) (By similarity). Along with GIT1, positively regulates microtubule nucleation during interphase. Phosphorylates FXR1, promoting its localization to stress granules and activity. Phosphorylates ILK on 'Thr-173' and 'Ser-246', promoting nuclear export of ILK.
Synonyms: IDDMSSD; PAKalpha; alpha-PAK; p65-PAK
Tractability: Small molecule: a structure with a bound ligand is known; a high-quality ligand is known; it has a high-quality binding pocket; it belongs to a druggable protein family. Antibody: UniProt places it where antibodies can reach, with high confidence; its Gene Ontology location is reachable by antibodies, with high confidence; the Human Protein Atlas places it where antibodies can reach. PROTAC: ubiquitination databases record sites on it; its protein half-life has been measured; a small molecule that binds it is known.
Target class: Protein Kinase; STE protein kinase PAKA subfamily; Enzyme; STE protein kinase group; Kinase; STE protein kinase STE20 family
Chemical probes: G-5555 (high quality), NVS-PAK1-1 (high quality), PF-03758309
Safety:
Unwanted effects reported when the protein is acted on. In parentheses: how it was acted on, where the effect was seen, and who reports it.
cardiac arrhythmia (cardiovascular system; source: Lamore et al. (2017))
Gene: Protein-coding gene on chromosome 11 (77,321,548 to 77,474,635, reverse strand). Ensembl gene ENSG00000149269.
Subcellular location: Cytoplasm; Cell junction, focal adhesion; Cell projection, lamellipodium; Cell membrane; Cell projection, ruffle membrane; Cell projection, invadopodium; Nucleus, nucleoplasm; Chromosome; Cytoplasm, cytoskeleton, microtubule organizing center, centrosome
Subcellular location (Human Protein Atlas): Cytosol; Plasma membrane
Pathways (Reactome):
Signal Transduction: CDC42 GTPase cycle; G beta:gamma signalling through CDC42; MAPK6/MAPK4 signaling; RAC1 GTPase cycle; RAC2 GTPase cycle; RAC3 GTPase cycle; RHO GTPases Activate ROCKs; RHO GTPases activate PAKs; RHO GTPases activate PKNs; RHOH GTPase cycle; RHOJ GTPase cycle; RHOQ GTPase cycle; RHOU GTPase cycle; RHOV GTPase cycle; VEGFR2 mediated vascular permeability
Developmental Biology: Activation of RAC1; EPHB-mediated forward signaling; Ephrin signaling; Sema3A PAK dependent Axon repulsion; Signal transduction by L1
Immune System: CD209 (DC-SIGN) signaling; CD28 dependent Vav1 pathway; FCERI mediated MAPK activation; Generation of second messenger molecules; Regulation of actin dynamics for phagocytic cup formation
Muscle contraction: Smooth Muscle Contraction
Gene Ontology:
Molecular function: collagen binding; gamma-tubulin binding; protein binding; protein kinase activity; protein serine kinase activity; protein serine/threonine kinase activity; small GTPase binding; ATP binding; protein kinase binding
Biological process: actin cytoskeleton organization; branching morphogenesis of an epithelial tube; cell migration; chromatin remodeling; DNA damage response; hepatocyte growth factor receptor signaling pathway; MAPK cascade; negative regulation of cell proliferation involved in contact inhibition; positive regulation of cell migration; positive regulation of cell population proliferation; positive regulation of intracellular estrogen receptor signaling pathway; positive regulation of microtubule nucleation; positive regulation of stress fiber assembly; protein localization to cytoplasmic stress granule; wound healing; cellular response to starvation; ephrin receptor signaling pathway; Fc-gamma receptor signaling pathway involved in phagocytosis; neuron projection morphogenesis; regulation of actin cytoskeleton organization; regulation of axonogenesis; regulation of MAPK cascade; stimulatory C-type lectin receptor signaling pathway; cellular response to insulin stimulus; cerebellum development; and 10 more
Cellular component: actin filament; cell-cell junction; chromosome; cytoplasm; cytosol; nucleoplasm; plasma membrane; protein-containing complex; ruffle; axon; dendrite; intercalated disc; nuclear membrane; Z disc; centrosome; focal adhesion; lamellipodium; ruffle membrane
Genetic constraint (gnomAD): Loss-of-function variants: 15 observed, 32.74 expected, observed/expected ratio (o/e) 0.46, 90% interval 0.31 to 0.7. The upper end of that interval is the gene's LOEUF score, 0.7, which puts it in group 2 of 6, group 1 being the genes least tolerant of losing a copy. Missense variants: 238 observed, 463.11 expected, observed/expected ratio (o/e) 0.51, 90% interval 0.46 to 0.57. Synonymous variants: 157 observed, 167.82 expected, observed/expected ratio (o/e) 0.94, 90% interval 0.82 to 1.07.
Homologues: Orthologues: dog PAK1 (99% identical), mouse Pak1 (99% identical), rat Pak1 (99% identical), guinea pig PAK1 (99% identical), chimpanzee PAK1 (96% identical), macaque PAK1 (95% identical), rabbit PAK1 (94% identical), pig PAK1 (92% identical), zebrafish pak1 (86% identical), tropical clawed frog pak1 (70% identical), Drosophila melanogaster Pak (66% identical). Paralogues in human: PAK3 (81% identical), PAK2 (75% identical), PAK5 (39% identical), PAK4 (37% identical), PAK6 (35% identical), MAP3K19 (26% identical), MAP3K1 (25% identical), TAOK1 (24% identical), MAP4K3 (24% identical), OXSR1 (23% identical), SLK (23% identical), STK26 (23% identical), and 23 more.
Diseases named in the same sentence as PAK1 in open-access papers:
PAK1 is named in the same sentence as 254 diseases in open-access papers, as found by Europe PMC text mining. Sharing a sentence is not in itself a finding about the gene and the disease. The quoted sentences say what the papers report.
breast carcinoma (142 papers, 2006 to 2026). "PAK1 amplifications, for instance, have been associated with poor prognosis, chemoresistance, and increased metastatic potential in breast cancer." (PMID 39756822, 2025). "PAK1 genomic amplification at 11q13 is prevalent in luminal breast cancer and PAK1 protein expression is associated with lymph node metastasis." (PMID 38660565, 2024). "In breast cancer, PAK1 associates with Janus-activated kinase (JAK2) to promote cancer stem population." (PMID 36830998, 2023). "Absolute and relative risk of death from breast cancer according to mean PAK1 copy number/tumour cell nucleus in primary tumours." (PMID 37368917, 2023). "In an attempt to delineate the basis of the heregulin/neuregulin-β1 (HRG)-triggered invasion of HER2-overexpressing breast cancer cells in late 1996, PAK1 signaling was discovered to play a causative role in mediating the invasiveness of breast cancer cells." (PMID 36830998, 2023). "Relative risk of death from breast cancer according to copy numbers of PAK1 and CCND1, and co-amplification of PAK1 and CCND1." (PMID 37368917, 2023). "The accumulation of active PAK1 in the nuclei of malignant cells and a causal link to breast cancer progression in mice have been demonstrated." (PMID 37190165, 2023). "The overexpression of PAK1 or amplification of the PAK1 gene has been associated with tumors such as breast cancer, ovarian cancer, colorectal cancer, hepatocellular carcinoma and many others." (PMID 38004560, 2023). "In this work, we show that Pak1-deficient breast cancer cells showed a dramatic reduction in CaMKII phosphorylation at residue T287, which is important for the activity of this kinase." (PMID 35111748, 2021). "This array was probed with lysates from wild type and Pak1 deficient breast cancer cells derived from murine tumors." (PMID 35111748, 2021). "The associations between PAK1 and breast cancer have been extensively investigated, of which the results indicated that this kind of potential therapeutic target participated in several progressive courses in malignancies 21-23." (PMID 33403050, 2021). "Down-regulated genes in HER2-negative cell lines are directly linked to HER2 overexpression and HER2-positive breast cancers (e.g., Stat, Ptpn1, Pak1, Efnb1)." (PMID 34775465, 2021). "Another substrate of PAK1, Integrin-linked kinase (ILK), can be phosphorylated by PAK1 at threonine 173 and serine 246 to promote breast cancer cell motility and proliferation." (PMID 32863957, 2020). "Amplified 11q13 and subsequent PAK1 expression has been identified in ovarian cancer and in breast cancer where 11q13 amplification is associated with poor prognosis." (PMID 27845911, 2017). "We demonstrate a distinct reduction in PRL-induced FAK auto-phosphorylation in T47D and TMX2-28 breast cancer cells overexpressing wild-type PAK1 (PAK1 WT) when compared to cells overexpressing either GFP or phospho-tyrosine-deficient mutant PAK1 (PAK1 Y3F)." (PMID 27542844, 2016). "A considerable number of differentially expressed genes between wild-type and PAK1 deficient human breast cancer cells were also found differentially expressed in mouse breast cancer cells." (PMID 27740936, 2016). "The PAK1 gene, which resides in 11q13.5, has previously been implicated in breast cancers and other cancers that contain this amplicon." (PMID 27740936, 2016). "In this study, we demonstrate that PAK1 amplification and overexpression are associated with poor clinical outcome in a large collection of luminal breast cancers." (PMID 25902869, 2015). "The association of PAK1 dysregulation with survival of breast cancer patients was evaluated at the protein level in an independent sample set of 1,108 estrogen receptor-positive, early-stage breast tumors." (PMID 25902869, 2015). "We demonstrate that focal genomic amplification and overexpression of PAK1 are associated with poor clinical outcome in the luminal subtype of breast cancer (P = 1.29 × 10−4 and P = 0.015, respectively)." (PMID 25902869, 2015).
breast carcinoma (continued). "Herein, we demonstrate that PAK1 gene amplification and protein overexpression are associated with poor clinical outcome in a large collection of luminal breast cancers." (PMID 25902869, 2015). "Several recent studies showed that overexpression of PAK1 is associated with poor differentiation in gastric cancer, colorectal cancer and breast cancer." (PMID 25182632, 2014). "Studies from other malignancies found that overexpression of PAK1 was associated with poor prognosis in colorectal cancer, ovarian cancer, and breast cancer." (PMID 25182632, 2014). "PAK1 overexpression is associated with poor prognosis in some tumor types, including breast cancer, gastric cancer, and colorectal cancer." (PMID 25182632, 2014). "In premenopausal breast cancer patients, Pak1 overexpression has been closely linked with tamoxifen resistance of tumors." (PMID 20426825, 2010). "Mutation of the Ebp1 PAK1 phosphorylation site results in inactivation of the ability of Ebp1 to repress transcription of cell cycle-regulated genes and inhibit breast cancer cell growth." (PMID 18283314, 2008). "The significant association between PAK1 and worse survival in skin cancer, as well as the trend toward reduced survival in lung and breast cancers, suggests that PAK1 could serve as a valuable prognostic marker in these malignancies." (PMID 39756822, 2025). "This suggests that loss of CRIPAK in breast cancer cells could lead to persistent PAK1 activation, potentially contributing to breast carcinogenesis." (PMID 40001545, 2025). "A previous finding in breast cancer cells suggests that decreased tumor angiogenesis in PAK1-deficient PCa tumor xenografts could be caused by reduced VEGF production by the PAK1-deficient PCa cells." (PMID 37190165, 2023). "We have also implicated pTyr-PAK1 in the regulation of breast cancer cell adhesion and demonstrated that phosphorylation of tyrsines 153, 201 and 285 of PAK1 regulates cell adhesion, contribute to maximal PAK1 kinase activity and increased ability to bind βPIX and GIT1." (PMID 27542844, 2016). "In contrast, PAK1 has been associated with Rac mediated invadopodia dissolution in a breast cancer cell line, thus PAK1 function in invadopodia may be cell type specific." (PMID 27765920, 2016). "Interestingly, PAK1 genomic amplification or protein overexpression are strongly associated with poor outcome for luminal (or estrogen receptor-positive) breast cancer patients." (PMID 25902869, 2015). "PAK1 overexpression was frequently observed and associated with breast cancer invasiveness." (PMID 25093037, 2014). "Other Pak family members have also been linked with breast cancer, especially Pak1." (PMID 23326684, 2012). "Other Pak kinases, particularly Pak1, have also been implicated in breast cancer, although the different Paks may function by different mechanisms." (PMID 23326684, 2012). "The pro-survival function of PAK1 in breast cancers might be another contributing factor to the association of elevated PAK1 expression and reduced clinical benefit in patients treated with tamoxifen." (PMID 21653999, 2011). "Mutation of the PAK1 phosphorylation site to glutamic acid, mimicking a phosphorylated state, completely abrogated the ability of Ebp1 to repress transcription, inhibit growth of breast cancer cell lines and contribute to tamoxifen sensitivity." (PMID 18283314, 2008). "In estrogen receptor-positive (ER+) breast cancer, PAK1 hyperactivation mediates resistance to endocrine therapy (ET) and CDK4/6 inhibitors by driving epithelial-to-mesenchymal transition (EMT) and MAPK pathway activation." (PMID 40001545, 2025). "Based on GeoMx DSP spatial multi‐omics analysis, it was identified that VEGFD and PAK1 expression levels were markedly increased in breast cancer cells co‐cultured with F. nucleatum." (PMID 40070022, 2025). "Increased expression of PAK1 in breast cancer cells increases cyclin D1 mRNA and protein levels and its nuclear accumulation." (PMID 40001545, 2025).